IL4 (interleukin 4)
Diseases named in the same sentence as IL4 in open-access papers (continued):
Sharing a sentence is not in itself a finding about the gene and the disease.
asthma (continued). "Subcutaneous injection with perilla seed water/ethanol extract, as a traditional oriental therapeutic herbal acupuncture, seemed to reduce IgE, IL-4, IL-5, and IL-13 in BALF in OVA-induced asthma in mice." (PMID 26064160, 2015). "IL-4 and IL-13 are required for the IgE class switching in B lymphocytes, and increased BAL levels of IL-4 and IL-13 are consistent with elevated allergen-specific IgE in serum and BAL fluid in the sheep asthma model." (PMID 26362930, 2015). "Focussing on genes of the Th2 pathway (IL4, IL4R, IL13, GATA3, STAT6), the authors demonstrated that the odds of asthma tended to decrease at the age of 10 years with increasing GATA3 methylation." (PMID 26052354, 2015). "Data collected from people with asthma and also in mouse models of asthma driven by inhalation of the model antigen ovalbumin (OVA) have shown that IL-4, IL-5, and IL-13 have potential to serve as an allergic asthma biomarker profile." (PMID 26346739, 2015). "By the fact that insulin infusion suppresses the expression of IL-4, ADAM-33, LIGHT, and LTBR and the plasma concentrations of NOM and MMP-9, the efficacy of insulin in the treatment of asthma needs to be assessed." (PMID 25642424, 2015). "Insulin decreased mRNA expression of IL-4, ADAM-33, and LTBR (lymphotoxin beta receptor), which are all potentially involved in pathogenesis of asthma." (PMID 26783384, 2015). "The current study aimed to investigate the expression of IL-4 and IL-13, as well as IL-6, IL-10 and TNF-α, in the sheep model of asthma following allergen challenge of the airways." (PMID 26362930, 2015). "Like our study that was also performed on unconcentrated BAL fluids using multiplex beads, these studies reported that IL-4 and IL-13 were undetectable in unconcentrated BAL fluids in asthma." (PMID 26011707, 2015). "Those are related to asthma and immune responses and include CCL8, CCL11, CCL24, IL4, IL6, IL10, IL13, IL1β, TNFą, and others." (PMID 26052354, 2015). "Interleukin-4 (IL-4) induces CD4+ T-cell proliferation and differentiation into Th2 cells that play an important role in asthma pathogenesis." (PMID 26466682, 2015). "In addition, ATF3 directly binds to CRE sites in the IL-4, IL-5 and IL-13 promoter regions and ATF3 binding sites were found enriched in a recent epigenomic analysis of regulated genes that play a role for TH2 memory cell differentiation and asthma susceptibility." (PMID 26459392, 2015). "In analogy, compound A has been shown to inhibit the OVA-induced IL-4 and IL-5 Th2 cytokine production in bronchoalveolar lavage fluid in a murine model of OVA-induced asthma." (PMID 25875480, 2015). "The levels of interleukin IL-4, IL-6 and IFN-γ, which are involved in OVA-induced asthma, in the bronchoalveolar lavage fluid (BALF) and the IgE level in the serum were examined by enzyme-linked immunosorbent assay (ELISA)." (PMID 26132811, 2015). "In response to HDM exposure, Ccsp-creTgfb1−/− mice displayed a reduction in key features of asthma pathology, namely diminished AHR, eosinophilia, pulmonary inflammation, type 2 cytokines, and IL-4-driven IgE production." (PMID 26588780, 2015). "In the study on the murine asthma model, acidic mammalian chitinase (AMC) was found to be upregulated and its expression was induced by cytokines IL-4 and IL-13." (PMID 25663327, 2015). "In our model of asthma SOCS3-siRNA treatment produce also a decreased expression in IL-5, IL-13, and IL-4." (PMID 24637581, 2014). "At the 5q31, we highlight IL4-590/IL4-RP2* T183 frequency, which is significantly lower in the reference set (8.8%) than overall asthma (16.8%, p-value = 0.019), persistent asthma (18.2%, p-value = 0.011), and moderate-severe asthma (26.7%, p-value = 3×10-4)." (PMID 25299150, 2014). "The ginsenosides, the constituents of KRGE were shown to reduce IL-4 production but increase IFN-γ production, resulting in Th1-type immune responses in an ovalbumin-induced murine model of asthma." (PMID 24756136, 2014).
asthma (continued). "MPP patients with allergic conditions had increased serum IgE levels and increased IL-4/INF-γ ratio, and IgE and Eosinophil Cationic Protein were further elevated in patients who eventually developed secondary asthma changes." (PMID 24977240, 2014). "The OVA-induced asthma group significantly increased the concentrations of TNF-α and IL-4 in BALF in comparison to the normal group (P < 0.01, P < 0.01)." (PMID 25101137, 2014). "Significant changes of IL-4, IL-10, and IFN-γ were observed in the asthma group in comparison to the normal group (P < 0.01, P < 0.05, and P < 0.01)." (PMID 24523826, 2014). "Previous studies have revealed that numerous types of inflammatory factors or cytokines play a critical role in classic asthma and CVA, including IL-5, IL-4 and eosinophilic cationic protein." (PMID 25187823, 2014). "Compared to the reference set, the most significant combinations are i) overall asthma IL13c.144/IL4-590*GT (p-value = 0.018); ii) persistent asthma IL13c.144/IL4-590*GT (p-value = 0.010) and iii) moderate-severe asthma IL4-590/IL4-RP2*T183 (p-value = 3x10-4)." (PMID 25299150, 2014). "A significantly higher percentage of CD4+Foxp3+ cells from asthma patients expressed IFN-γ (P = 0.01), IL-4 (P = 0.004) and CD25 (P = 0.04), whereas the percentage of CD4+IL-10+ cells expressing Foxp3 was significantly decreased in asthmatics (P = 0.03)." (PMID 25132806, 2014). "Studies in other models (asthma, trauma) demonstrated that Th1 cytokines such as IL-2 and IFN-gamma were increased whereas Th2 cytokines such as IL-4, IL-10 and IL-13 were suppressed." (PMID 24732949, 2014). "Instead of the commonly used animal model of asthma induced by OVA, our mouse model showing increased eosinophils and high expression of IL-4, IL-5 and IL-13 detected in BALF and lung tissue is considered to bear a closer resemblance to human asthma." (PMID 24671176, 2014). "By contrast, levels of IL-4 were reduced significantly, but levels of IFN-γ increased markedly, in the mice of the anti-NGF group when compared with those in the asthma and control-IgG groups." (PMID 25289030, 2014). "The results demonstrated that the levels of IL-4 and TNF-α in the sihuangxiechai decoction treated group were significantly reduced compared with the asthma group." (PMID 25101137, 2014). "Mast cells have been shown to play a key role in asthma through their release of a variety of mediators, including histamine, PGD2, tryptase, IL-4 and IL-5." (PMID 23849630, 2013). "TSLP can induce multiple signaling pathways in asthma, including STAT6, IL-4, IL-1β and TNFα, p38 and Jun kinase (JNK )." (PMID 24167583, 2013). "Both in vivo and in vitro studies confirmed that Vitamin A and ATRA induce Th2 bias and promote Th2 cytokines realise, such as IL-4, IL-5, IL-13 and GATA-3, which is one of the major characteristics of asthma." (PMID 24204796, 2013). "Sprr2 transcription can be also regulated by IL4/IL13/Stat6, as described in an experimental asthma mouse model." (PMID 23844115, 2013). "Th2 cytokines IL-13 and IL-4, which were overexpressed in the OVA-induced asthma model, were suppressed by both doses of ACA." (PMID 23451048, 2013). "IL2, IL4, IL5, IL6, IL13, and TNFαhave been reported to enhance asthma in humans, and Th1 cells have been shown to suppress Th2 cells through the release of IFN-γ." (PMID 23781124, 2013). "The decrease of IL-4 mRNA expression by the action of SHS suggests that SHS also has a potential to protect and/or treat diseases such as severe asthma." (PMID 23346216, 2012). "For other asthma-relevant genes such as TNF, IL-4, IL-10, CCL12 (MCP-5), CCL5 (RANTES), and CCR3, there were no significant IL-13-inducible or statin effects on gene expression." (PMID 22583375, 2012). "We previously demonstrated that simvastatin ameliorates allergic eosinophilic airway inflammation, decreases IL-13 and IL-4 levels in lung lavage fluid, and improves airway hyperreactivity (AHR) in the ovalbumin mouse model of asthma." (PMID 22583375, 2012).
asthma (continued). "As same with IL-2/IL-4 model, PP2A was also significantly phosphorylated at Thr307 in PBMCs of severe asthma." (PMID 22205926, 2011). "Th2 lymphocytes are the key orchestrators of this inflammation, initiating and propagating inflammation through the release of their cytokines, IL-4, IL-5, and TNF-α in turn recruiting and activating eosinophils, the effector cells in asthma." (PMID 20953388, 2011). "A number of biological agents have been developed to target cytokines thought to play an important role in asthma pathogenesis, including monoclonal antibody blockers of TNF-α, IL-5, IL-4 and IL-13." (PMID 21896202, 2011). "It has been demonstrated in animal models of asthma that allergens can elicit TH2 inflammation and that IL-4 is essential in this response." (PMID 20552026, 2010). "Percentage proportions of CD4+ T cell staining positively for IL-2, IL-4, IL-10, IL-13, IFN-γ, and TNF-α in unstimulated whole blood were similar in children with asthma compared to healthy controls." (PMID 21197090, 2010). "In a mouse model of experimental asthma, adoptive transfer of OVA specific TH1 cells reversed in a concentration-dependent manner TH2 cell derived IL-4 production, BAL eosinophilia and bronchial hyperresponsiveness." (PMID 20976014, 2010). "In asthma, CCR8 was expressed by 30.3±3.0% and 28.9±7.8% of the IL-4+- and IL-13+-producing BAL CD3+ cells, respectively." (PMID 20455898, 2010). "The preponderance of IL-4 and IL-13 relative to the type 1 cytokine IFN-γ is believed to promote feed-forward mechanisms of allergic inflammation in asthma." (PMID 20667106, 2010). "In contrast to the effects of IL-4 and IL-13, inhalation of IFN-γ decreases eosinophilic inflammation in the airways of subjects with asthma and treatment of mouse airways with IFN-γ inhibits eosinophilic airway inflammation." (PMID 20953328, 2010). "Interaction analysis between IL-4/IL-13 and their shared receptor is of particular interest because gene-gene interactions may modify the effects of individual SNPs in the IL-4/IL-13 pathway, and evidence of epistasis has been reported in a asthma and type 1 diabetes." (PMID 18625055, 2008). "Furthermore, most forms of asthma are characterized by abundant Th2 cytokine secretion (e.g IL-4, 5, 9 and, in particular, IL-13), and the over-expression of these cytokines in transgenic mouse models has been shown to reproduce numerous features of asthma including subepithelial fibrosis." (PMID 18348727, 2008). "On the other hand, when asthma became chronically severe, Th1 cytokines became the main player because of the very high level of IFN-γ and low level of IL-4." (PMID 19087256, 2008). "The synthesis of many inflammatory mediators such as TNFα, IL-4, IL-5, IL-8, RANTES and eotaxins, thought to be important in asthma pathogenesis, are regulated through activation of p38 MAPK." (PMID 18315837, 2008). "In asthma, blood CD4+ T cells express increased mRNA for interleukin (IL)-4, IL-5, and granulocyte macrophage colony stimulating factor, and IL-5 mRNA expression correlates with asthma severity and eosinophilia." (PMID 16393658, 2006). "IL4 is a pleiotrophic TH2 cytokine and impacts on the development of asthma and atopy in part through its role in the differentiation to a TH2 phenotype of T cells." (PMID 16759385, 2006). "The present data emphasize the essential role of Th2 cell produced IL-4 and IL-5 in the induction of asthmatic clinical symptoms in patients with CRS-asthma." (PMID 16677400, 2006). "The patients included in the present study had frequent asthmatic attacks, with signs of wheezing and higher levels of IgE and IL4 and low levels of FEV1 %Pre that are characteristics of asthma." (PMID 15710045, 2005). "Intriguingly, the clinical success of IL-4 pathway inhibitors (such as dupilumab, which blocks IL-4Rα, or various JAK inhibitors) in managing Th2-driven inflammatory diseases like atopic dermatitis and asthma provides a compelling precedent." (PMID 40864740, 2025).
asthma (continued). "Additionally, we explored the correlations between the microbial profiles and inflammatory cytokines known to play key roles in asthma pathogenesis, including IFN-γ, IL-4, IL-5, IL-13, IL-17A, IL-10, and TGF-β1." (PMID 40871265, 2025). "Consequently, asthma symptoms are exacerbated by the promotion of an increase in CD4+ Th2 cells and the further secretion of cytokines, such as IL-4, IL-5, and IL-13." (PMID 41155294, 2025). "The secretion of IL-4, IL-5 and IL-13 cytokines by these cells drives chronic inflammation and excessive immune responses in the airways, thereby further strengthening our understanding of TH2-type immune responses in asthma." (PMID 39980673, 2025). "Furthermore, this study utilized network pharmacology to identify pivotal asthma treatment targets for YKS, including AKT1, TNF, IL1B, EGFR, IFNG, IL4, CASP3, and PTGS2." (PMID 40420184, 2025). "Another study revealed that miR‐221‐3p could increase IL‐4 secretion in mast cells through a pathway involving PTEN, p38, and NF‐κB in a murine asthma model." (PMID 40131162, 2025). "Interestingly, hybrid Th2/Th17 cells expressing both IL‐4 and IL‐17 were identified in BAL fluid and blood from patients with severe asthma, correlating with eosinophil counts and IgE levels." (PMID 40016948, 2025). "Eosinophil-deficient (iPHIL) mice and mice lacking IL-4/IL-13 producing eosinophils displayed a reduced ILC2 response in HDM- and OVA-induced asthma models." (PMID 40276331, 2025). "Thus, prolonged treatment with a combination of IL-4 and IL-13 downregulated TSLP secretion and IFNλ1 gene expression, while inducing IFNβ expression, especially in BECs from asthma patients." (PMID 40370530, 2025). "Eosinophils from S-2P-vaccinated infected mice showed enrichment in the IFN-γ module, but not the Asthma or IL-4 modules." (PMID 41329757, 2025). "All other macrophage responses to IL-4, IL-13, and combined IL-4/IL-13 stimulation fell within the range of responses seen in donors without asthma." (PMID 41159038, 2025). "Biologic therapies target type 2 inflammatory mediators, such as immunoglobulin E (IgE), interleukin-4 (IL-4) and interleukin-5 (IL-5), and thymic stromal lymphopoietin (TSLP), thereby reducing asthma exacerbations and OCS use while improving QOL and lung function." (PMID 40861628, 2025). "In contrast, the predominantly Th2-induced cytokine IL-4 was significantly higher in the asthma group compared with the other disease groups and was not significantly different between patients with CF and control participants (unadjusted P = .1)." (PMID 40876742, 2025). "Eosinophilic airway inflammation and high IL-4, IL-5, and IL-13 levels define T2-high asthma, which can be allergic or non-allergic, depending on atopy." (PMID 40486460, 2025). "In asthma patients, it is reported that CRTH2+ circulating Tregs are characterized by increased IL-4 production and reduced immune suppressive function, while CCR6+ Tregs are more likely to differentiate into pathogenic Th17-like cells, contributing to the pathology of allergic asthma." (PMID 40933988, 2025). "Moreover, 1,8-cineole downregulated the levels of pro-inflammatory cytokines, such as IL-1β, IL-4, IL-6, IL-13, IL-17A, and TNF-α, in the BALF of animal asthma models sensitized with ovalbumin, house dust mite, and cigarette smoke." (PMID 40244178, 2025). "Th2‐high asthma is characterized by eosinophilic airway inflammation, also known as type 2 inflammation, primarily mediated by Th2 and ILC2 cells and involving pathways such as IL‐4/IL‐13, IL‐5, and IL‐25/IL‐33/TSLP." (PMID 41310922, 2025). "According to the GRADE system, the certainty of evidence for the asthma daytime and nighttime symptom scores, FEV1, FVC, PEF, and the levels of TNF-α, IFN-γ, and IL-4 was classified as very low, underscoring the need for additional rigorously designed studies to validate these findings." (PMID 41561940, 2025).
asthma (continued). "First, PDGF‐BB was employed to activate ASMCs; however, other growth factors (e.g., TGF‐β, EGF, and FGF) and inflammatory cytokines (for example, IL‐4, IL‐13, and TNF‐α) may also contribute to ASMC dysfunction in diseases such as asthma." (PMID 40338178, 2025). "Additionally, compared to the Asthma + Vehicle group, the IDF-11,774 group exhibited a significant decrease in IL-4, IL-5, IL-13, and IgE." (PMID 39061007, 2024). "Promising work by Wawrzyniak and others in primary human cells were able to reconstitute barrier function, damaged by IL4 and IL13 exposure, from asthmatic patients by inhibiting histone deacetylases (upregulated in asthma), resulting in junctional protein synthesis." (PMID 38529406, 2024). "Most asthma biologics that are approved by the US Food and Drug Administration (FDA) target T2 inflammation with specific monoclonal antibodies to IgE, and the IL-5 and IL-4/IL-13 signaling pathways." (PMID 39194521, 2024). "Furthermore, compared to the Asthma + oe-NC + IDF-11,774 group, the Asthma + oe-MDM2 + IDF-11,774 group demonstrated a significant increase in IL-4, IL-5, IL-13, and IgE levels." (PMID 39061007, 2024). "Biologics targeting IgE, IL-5, IL-4/IL-13, and TSLP are crucial in severe asthma treatment." (PMID 38525773, 2024). "There are other experimental studies on BALF cytology and cytokine response (IL-4, Il-5, IL-13, IL-17 and IFN-γ) in animals only with individual exposure to OVA in OVA-induced asthma; the impact of anti-Il-17 or dexamethasone treatment alone in this model was evaluated." (PMID 38543124, 2024). "The serum levels of TNF‐α (p = 0.025), IFN‐γ (p = 0.011), CCL22 (p = 0.022), IL‐12p70 (p = 0.021), CXCL10 (p = 0.028), CCL2 (p = 0.028), CCL13 (p = 0.024), IL‐4 (p = 0.026), IL‐13 (p = 0.024), and CCL11 (p = 0.028) were found to be downregulated in stable asthma when compared to acute asthma." (PMID 39508721, 2024). "Mast cells play a key role in asthma pathophysiology and airway remodelling through the release of a plethora of cytokines (e.g. TSLP, IL-33, IL-25, IL-4, IL-13 and TGF-β) and angiogenic factors (e.g. VEGF-A), as well as other inflammatory mediators and bronchoconstrictors." (PMID 38609094, 2024). "Additionally, research has indicated that a significant decrease in IL-13 levels occurred with a reduction the secretion of eosinophils, which produce large amounts of IL-4 and IL-13, in an OVA-induced asthma mouse model." (PMID 38732497, 2024). "Type 2-high and type 2-ultra-high asthma again involve IL-4, IL-5, and IL-13, while type 2-low asthma, due to the lack of biomarkers, is described as a type with different mechanisms of disease, including IL-1β, IL-6, or neutrophil infiltration." (PMID 38785919, 2024). "In addition, treatment with tectochrysin or dexamethasone significantly reduced the levels of IL-4 and IL-5 as well as the IL-4/IFN-γ ratio in BALF of asthmatic mice, indicating the potential of tectochrysin as a therapeutic agent for asthma." (PMID 39759448, 2024). "It has also been shown that SEMA4A-Plexin-D1 contributed to the elevated IL-4 and IL-17 in patients with systemic sclerosis (SSc), and the same manner can be seen for other T CD4+ mediate diseases, including asthma, rheumatoid arthritis (RA), and multiple sclerosis (MS)." (PMID 38148815, 2024). "IL-13/IL-4/JAK/STAT6 is a key signaling pathway essential to type 2 inflammation and allergies, and strategies to target it have proven effective to treat atopic dermatitis, asthma and to prevent itching." (PMID 39345572, 2024). "Interestingly, the expression of miR-181a in the lung of allergic rhinitis mice reduced the count of eosinophils in BALF and decreased IL-4, IL-5, and IL-13 by targeting high mobility group box 1 (HMGB1), resulting in retarded development of asthma." (PMID 38337625, 2024).